INS (insulin)
Diseases named in the same sentence as INS in open-access papers (continued):
Sharing a sentence is not in itself a finding about the gene and the disease.
Insulin resistance (continued). "While it has not been specifically shown to lower the risk of cardiovascular events in patients with PCOS, existing mechanistic and clinical evidence supports its use as a protective measure against the cardiovascular risks associated with insulin resistance and excess insulin." (PMID 39459443, 2024). "Besides, metformin has been shown to ameliorate neuronal insulin resistance in an in vitro neuronal insulin-resistant model also showing hallmark AD-like changes and to inhibit neuronal damage by upregulating GLP-1 receptor (GLP1R)." (PMID 39170185, 2024). "Whereas general obesity and central adiposity, in particular, are the primary factors responsible for the development of insulin resistance, postprandial increases in insulin secretion causes a further expansion of the adipose tissue mass, which further worsens insulin resistance." (PMID 38890501, 2024). "Intensive insulin therapy may increase insulin resistance leading to increased insulin dose, thus further promoting insulin-associated weight gain." (PMID 39274516, 2024). "In addition, the rise in insulin resistance and the increased demand for insulin during pregnancy, can also unveil an underlying type 1 diabetes (T1DM)." (PMID 38601785, 2024). "This is not entirely in agreement with previous studies by some of our group that showed that β-cell specific PTEN-knockout mice have enhanced insulin sensitivity and are completely protected against insulin resistance induced by high fat diet due to neuronal PTEN deficiency." (PMID 38578954, 2024). "Evidence have indicated that pretreating cells with protein synthesis inhibitors (such as cycloheximide), can alleviate insulin resistance caused by glucocorticoids (dexamethasone) or high-glucose environments, suggesting the significant role of protein synthesis load in insulin sensitivity." (PMID 39749015, 2024). "Consistent with the complexity of insulin signaling, past efforts have elucidated many mechanisms that are implicated in insulin resistance, that is, genetic abnormalities or environmental stress (overeating) dysregulates molecules involved in proximal and distal insulin signaling." (PMID 39049964, 2024). "Furthermore, they found that the insulin methylation index in cfDNA was associated with insulin resistance and with newborn birth weight." (PMID 39057684, 2024). "Elucidating the signal transduction mechanisms involved in the cardiac insulin signaling response could potentially pave the way for identifying therapeutic approaches to treat cardiac diseases associated with insulin resistance." (PMID 39026321, 2024). "Disturbances in the levels of essential elements may lead to the development of GDM by causing disorders in insulin sensitivity, insulin resistance and glucose intolerance." (PMID 39596259, 2024). "The pathogenesis of T2D includes a progression from chronic insulin resistance and the loss of β-cell mass and function to a resultant inadequate capacity of the β-cells to secrete insulin in sufficient quantities to compensate for the decrease in insulin sensitivity." (PMID 38611359, 2024). "Regarding insulin resistance and secretion, breastfeeding duration was negatively associated with HOMA-IR, HOMA-B and AUC (p<0.01), but positively associated with Matsuda and the insulin resistance-adjusted insulin secretion (ISSI-2) (all p≤0.01) at 1 year postpartum in model." (PMID 38772880, 2024). "Furthermore, the accumulation of visceral obesity leads to insulin resistance, resulting in elevated levels of insulin and IGF-1, both of which further contribute to the risk of developing prostate cancer." (PMID 38214779, 2024). "We tested the hypothesis that a decrease in EE that occurs with TN causes insulin resistance and that this reduction in insulin action and EE is reversed upon short term (<12h) transition to RT." (PMID 38354854, 2024). "Consequently, the liver uptakes and accumulates lipids, affects insulin signaling, and causes hepatic insulin resistance." (PMID 39411175, 2024).
Insulin resistance (continued). "This implies that higher lipid buildup in the skeletal muscle and liver may cause disruption with insulin signaling that results in insulin resistance." (PMID 39807459, 2024). "Men with insulin resistance experience more significant muscle mass loss with age compared to insulin-sensitive individuals, and different muscle groups, like type IIb fibers, may show varied responses." (PMID 38473418, 2024). "It has been shown that palmitate causes insulin resistance in vivo and in vitro in hypothalamic neurons, but few studies have addressed the effect of palmitate on insulin resistance in glial cells, and the mechanisms underlying such an effect remain to be determined." (PMID 38535321, 2024). "Finally, we used a single-point insulin sensitivity estimator to indirectly reflect the degree of insulin resistance and assess its mediating effect on the association between IMAT area and decreased renal function." (PMID 38886276, 2024). "The scientific literature analyzed and used to for this article was found on PubMed, Scopus, Science Direct, etc, using the following keywords: insulin, insulin signaling, insulin resistance, hyperinsulinemia, cardiovascular risk factors, cardiovascular system, cardiovascular diseases." (PMID 38545338, 2024). "Systemic inflammation plays a role in obesity-related insulin resistance but may also affect glucose and insulin metabolisms in individuals with other causes of inflammation." (PMID 38473112, 2024). "In this study, GL was found to significantly stimulate basal glucose uptake in C2C12 myotubes, but its effect on insulin resistance, a condition often associated with impaired insulin signaling and reduced glucose uptake, remains unclear." (PMID 38611884, 2024). "Contributing environmental factors include poor diet, aging, alcohol consumption, smoking, and especially obesity, which predisposes individuals to insulin resistance and exacerbates the condition by altering genes critical for insulin signaling and glucose tolerance." (PMID 40226688, 2024). "A reduction in insulin-stimulated glucose storage is a hallmark of insulin resistance." (PMID 38354854, 2024). "It is widely recognized that insulin resistance is a crucial metabolic dysfunction commonly linked to type 2 DM, referring to the impaired ability of peripheral target tissues, including adipose tissue, to effectively respond to insulin." (PMID 38399315, 2024). "In addition, considering the combination of moderate intensity exercise training and insulin therapy, it can effectively amplify the effect of insulin resistance associated diabetes induced intracellular apoptosis of testis." (PMID 38225568, 2024). "Both insulin resistance and decreased insulin secretion are considered to be the main causes." (PMID 38397965, 2024). "The main cause of T2DM is insulin resistance, initially pancreatic β-cells maintain glucose homeostasis by an increase in insulin production, but over time, insulin secretion decreases and even pancreatic β-cell failure, resulting in varying degrees of hyperglycemia." (PMID 38388535, 2024). "Increased insulin resistance with hyperinsulinemia, excessive insulin secretion as a compensatory response may raise a risk of developing DM and its cardiovascular diseases." (PMID 39969290, 2024). "The decreased physical activity could participate to the development of insulin resistance since it is well established that physical activity and insulin sensitivity are tightly linked to each other." (PMID 38553002, 2024). "In this cross-sectional study, we investigated the associations of two different surrogate measures of insulin resistance, including: non-insulin-based indexes (TG/ HDL, TyG, TyG-BMI, and METS-IR) and empirical indexes (EDIR and ELIR) with odds of having hyperuricemia." (PMID 38172828, 2024). "This indicates that abnormal insulin signaling in the skeletal muscles may cause insulin resistance." (PMID 39430205, 2024).
Insulin resistance (continued). "Interestingly, the mechanism underlying the reduced insulin-stimulated glucose uptake in PCOS skeletal muscle likely differs from insulin resistance in BMI-matched controls." (PMID 38180081, 2024). "Moreover, the increased level of these cytokines has already been reported to be associated with the occurrence of T2DM by modulating insulin signaling pathways favoring insulin resistance." (PMID 39596058, 2024). "However, female but not male SD mice under a normal chow diet displayed glucose intolerance and insulin resistance, which are associated with impaired insulin signaling/AKT in the skeletal muscle and liver." (PMID 38393018, 2024). "Furthermore, high consumption of sugar-sweetened beverages that result in a spike in blood glucose and insulin levels is positively associated with the development of glucose intolerance and insulin resistance, all of which are key contributors to obesity." (PMID 38612997, 2024). "The two main reasons for T2DM are impairment of insulin secretion and resistance to the action of insulin (insulin resistance), which may be caused by both genetic factors and obesity." (PMID 38254789, 2024). "Weight gain causes insulin resistance (IR), which results in higher insulin requirements." (PMID 39906033, 2024). "Since high WC potentially causes insulin resistance, we hypothesized that insulin action may affect these associations." (PMID 38206990, 2024). "Insulin resistance can cause β-cell failure due to long-term increased insulin demand." (PMID 38297165, 2024). "Reduction associated with higher GGT levels and fasting serum insulin; its cell wall components have anti-inflammatory effects; decrease may worsen insulin resistance." (PMID 39664063, 2024). "Fat intake may therefore be implicated in miR-221 modulation and, as the evidence associates miR-221 with insulin levels, it might also be involved in the development of insulin resistance." (PMID 38542682, 2024). "In addition, therapy with subcutaneous insulin injection bypasses the normal insulin delivery into the portal vein and causes “iatrogenic hyperinsulinemia,” which causes whole-body insulin resistance." (PMID 38989268, 2024). "Insulin resistance (IR), a key part of metabolic syndrome (MetS), refers to the diminished ability of an individual’s cells and tissues to respond effectively to insulin and causes a compensatory rise in circulating insulin levels, thereby sustaining normoglycaemia." (PMID 39737155, 2024). "Moreover, high concentrations of TNF, IL-1β and IL-6 in circulation cause insulin resistance in hepatocytes and skeletal muscle cells and inhibit insulin production by the pancreas." (PMID 39107476, 2024). "In addition to the risk of hypoglycemic episodes, the intensive insulin treatment to insulinopenic individuals has been associated with the development of insulin resistance." (PMID 38892513, 2024). "However, increases in IL-8 can cause insulin resistance and thus worsen hyperglycemia via inhibition of insulin-induced Akt phosphorylation." (PMID 39234180, 2024). "However, those in the glucose control group (n = 25) or a casein-supplemented group (n = 20) showed modest levels of weight loss but increases in insulin levels and insulin resistance from baseline to the end of follow-up." (PMID 39796517, 2024). "PCOS is characterized by insulin resistance; therefore, SNPs linked to the insulin signaling pathways may contribute to the development of PCOS's clinical features." (PMID 38468402, 2024). "Although patients with insulin resistance may have a reduced risk of hypoglycemia, other factors associated with decreased sensitivity to insulin may have a detrimental effect on vascular health and disease outcomes." (PMID 39335526, 2024). "Omentin-1’s potential to enhance insulin sensitivity suggests that it could be a therapeutic target for individuals with insulin resistance or those at risk of developing type 2 diabetes." (PMID 38397886, 2024).
Insulin resistance (continued). "Furthermore, higher vitamin D concentrations positively impact insulin sensitivity, and prior research has demonstrated an inverse association between insulin resistance and renal clearance of SUA." (PMID 38794730, 2024). "These molecules antagonize insulin-mediated metabolic processes and cause insulin resistance." (PMID 38961093, 2024). "Taken together with existing literature, our results indicate that the progression from insulin sensitivity to insulin resistance and T2D is associated with an increase in choline metabolism and a shift to CDP–choline and CDP–ethanolamine pathways over the TMAO pathway." (PMID 39195553, 2024). "Additionally, an analysis of four risk factors (fasting insulin, insulin resistance, total testosterone level, and estradiol level) was performed to investigate the underlying mechanisms linking statistically significant meat intake to acne." (PMID 38873457, 2024). "Similarly, since the hypoglycemic effect of SGLT2is is insulin-independent, they have a low risk of hypoglycemia and are effective in patients with high insulin resistance." (PMID 39497800, 2024). "Second, insulin resistance causes high insulin levels in the blood." (PMID 39737155, 2024). "By reducing oxidative stress and inflammation, bilirubin may help improve insulin sensitivity and reduce the risk of developing insulin resistance and type 2 diabetes." (PMID 38195551, 2024). "It has been observed that mice with reduced numbers of pro-inflammatory Th1 cells have reversed obesity-associated insulin resistance, suggesting a causal relationship between T cell-driven immune activation and disturbed insulin sensitivity, but the mechanisms in humans are less clear." (PMID 39641064, 2024). "Our data suggest that higher serum myostatin levels are associated with lower insulin sensitivity in otherwise healthy adults, aged 20–65 years, with overweight/obesity, independent of other risk factors known to be associated with insulin resistance, namely BMI, visceral adiposity, and sex." (PMID 39261976, 2024). "Consequently, the development and manifestation of PCOS can be associated with insulin-related metabolic abnormalities, such as insulin resistance and compensatory hyperinsulinemia and vice versa." (PMID 38540173, 2024). "It was clearly demonstrated that the elevated serum CRP concentration is associated with higher fasting insulin and glucose and HbA1c levels, suggesting a possible role of inflammation in processes closely related to the MetS such as insulin resistance and glucose intolerance." (PMID 39766234, 2024). "Juicer Broccoli reduces the levels of IL-1β and IL-6 in cells, which helps to alleviate the decrease of insulin secretion and insulin resistance caused by T2DM, improve the disorder of glucose metabolism, reduce inflammatory response and cardiovascular disease risk." (PMID 38254574, 2024). "Previous investigations have demonstrated that patients with impaired glycemic indices, such as elevated levels of fasting blood glucose (FBS), fasting insulin (FI), and Homeostasis Model Assessment-Estimated Insulin Resistance (HOMA-IR), face an elevated risk of developing NAFLD." (PMID 38729941, 2024). "Previous studies have reported that insulin resistance improvements after bariatric surgery are related with weight loss and a second hypothesis, it is that sleeve gastrectomy may improve insulin action via gut hormone modification, too." (PMID 38570479, 2024). "Another clinical study found that supplementation with 1500 mg of green tea extract [856 mg of epigallocatechin gallate (EGCG)] for 16 weeks caused a significant reduction in fasting insulin, insulin resistance, and glycated hemoglobin in obese individuals with T2D." (PMID 38921462, 2024).
Insulin resistance (continued). "Prolonged GPx-1 activation in animal models may disrupt insulin signaling pathways, and GPx-1 overexpression has been associated with obesity and insulin resistance in experimental settings, whereas its reduction tends to mitigate these effects." (PMID 39469571, 2024). "Insulin resistance serves as a fundamental hallmark of MetS, and within the kidneys, a pivotal organ in metabolic processes, diverse cells within both the glomerular and renal tubular compartments exhibit a dependency on insulin signaling." (PMID 38890983, 2024). "These structural and functional changes in the skeletal muscle induced by defective insulin action are suggested to be associated with muscle weakness and reduced endurance capacity, which in turn may exacerbate insulin resistance." (PMID 38612885, 2024). "Moreover, defects in insulin signaling in microvascular endothelial cells at the BBB strongly contribute to brain insulin resistance in Alzheimer’s disease in association with β-amyloid pathology." (PMID 39456952, 2024). "Elevated serum ferritin levels in women are associated with an increased risk of GDM, which may be attributed to heightened insulin resistance and increased insulin secretion from pancreatic β-cells, potentially leading to β-cell exhaustion." (PMID 39583387, 2024). "There was a critical need to measure insulin action to establish whether insulin resistance was a causal factor in T2D." (PMID 38299589, 2024). "Tacrolimus results in not only insulin secretion deficiency but also insulin resistance." (PMID 38474169, 2024). "Moreover, POMC neuron Bbs1 gene deletion caused glucose intolerance and insulin resistance, whereas loss of the Bbs3 gene in these same neurons is associated with normal insulin sensitivity and mild glucose intolerance." (PMID 38223458, 2024). "Reduced insulin action due to insulin resistance is linked to abnormal cardiac metabolism in HF." (PMID 38673896, 2024). "Given that insulin resistance is a hallmark of type 2 diabetes and is closely linked to chronic inflammation, BHB’s ability to protect insulin signaling function could be pivotal for individuals with hyperuricemia and concurrent insulin resistance." (PMID 39728460, 2024). "The two most prevalent forms are diabetes mellitus type I and II due to autoimmune β-cell destruction, usually leading to absolute insulin deficiency, and progressive loss of adequate β-cell insulin secretion, consequent to insulin resistance and metabolic syndrome, respectively." (PMID 39768436, 2024). "Concurrently, insulin resistance contributes to atherosclerosis and plaque progression through multiple pathways, including alterations in traditional cardiovascular risk factors and the suppression of insulin signaling pathways." (PMID 38954387, 2024). "The effects of insulin stimulation on the O-GlcNAc signaling pathway are particularly well studied since disruption of O-GlcNAc homeostasis has been implicated in the pathogenesis of insulin resistance." (PMID 38783961, 2024). "The greater elevation of glucose and insulin after consuming the tortilla chip snack might suggest that such high-carbohydrate snacks could be a risk factor in the development of insulin resistance and type 2 diabetes." (PMID 38999832, 2024). "Many studies based on animal models and human populations confirmed that supplementation with folic acid decreased insulin resistance, induced DNA methylation in genes associated with obesity and insulin secretion, and improved blood glucose control in obese patients with type 2 diabetes." (PMID 39060963, 2024). "Insulin resistance is a hallmark of obesity in which the metabolic response to insulin is impaired." (PMID 39684547, 2024). "Overactivation of TLR4 during chronic neuroinflammation reduces insulin sensitivity and causes insulin resistance, directly through pro-inflammatory kinases and reactive oxygen species, or indirectly through the release of pro-inflammatory cytokines and insulin-desensitizing factors." (PMID 39830652, 2024).